FOXO3 (forkhead box O3)
Diseases named in the same sentence as FOXO3 in open-access papers (continued):
Sharing a sentence is not in itself a finding about the gene and the disease.
gastric cancer (continued). "In the present study, we found three types of gastric cancers according to the expression and subcellular localization of FOXO3." (PMID 33795838, 2021). "In the present study, we found three types of gastric cancers according to the expression and subcellular localization of FOXO3: the FOXO3-Nuc, FOXO3-Cyt, and FOXO3-negative types." (PMID 33795838, 2021). "We therefore examined the FOXO3 subcellular localization of these gastric cancer cells by immunocytochemistry." (PMID 33795838, 2021). "We finally examined the effect of the inhibition of PI3K-AKT signaling in FOXO3-Cyt-type human gastric cancer using the gastric cancer-derived organoid lines GC19 and GC26." (PMID 33795838, 2021). "Among the three subtypes of gastric cancer, we show here that FOXO3-Nuc-type cells are resistant to endogenous FOXO3-induced growth suppression." (PMID 33795838, 2021). "We next examined the FOXO3 expression in gastric cancer cell lines by immunoblotting and found that 5 of the 10 lines showed an elevated FOXO3 expression (asterisks)." (PMID 33795838, 2021). "In pancreatic and gastric cancers, miR-629 acts as an oncogene, promoting cell proliferation and inhibiting apoptosis by targeting FOXO3." (PMID 33221765, 2020). "Inhibition of PARP1 induced nuclear localization of FOXO3, which had an anti-proliferative effect on gastric cancer cells." (PMID 29784019, 2018). "Indeed, microRNA-582 can promote gastric cancer liver metastasis via the PI3K/AKT/Snail pathway mediated by FOXO-3." (PMID 37180578, 2023). "Furthermore, the expression of Act-ER FOXO3 by an endogenous promoter significantly suppressed gastric tumorigenesis in Gan mice, a model of gastric cancer." (PMID 33795838, 2021). "Therefore, endogenous FOXO3 can play a tumor-suppressor role via its nuclear accumulation in FOXO3-Cyt-type gastric cancer." (PMID 33795838, 2021). "Furthermore, downregulated expression of GATA6-AS1 activates the PI3K/AKT/Snail signaling pathway via regulation of miR-582/FOXO3 axis and subsequently promote the proliferation and metastasis of gastric cancer cells." (PMID 34429758, 2021). "Furthermore, the high expression of FOXO3 in gastric cancer was correlated with a good prognosis, suggesting a tumor-suppressor role of FOXO3." (PMID 33795838, 2021). "In FOXO3-positive gastric cancers, a clear nuclear accumulation was found in 22 cases (44.0%) (FOXO3-Nuc), while FOXO3 was broadly distributed to the cytoplasm in the 20 remaining FOXO3-positive cases (40.0%) (FOXO3-Cyt)." (PMID 33795838, 2021). "In conclusion, we classified gastric cancer into three types based on the FOXO3 expression pattern." (PMID 33795838, 2021). "In contrast, in FOXO3-Cyt gastric cancer cells, we showed that the nuclear translocation of FOXO3 by the expression of Act-ER FOXO3 from an endogenous promoter or inhibition of PI3K-AKT signaling suppressed the colony formation and proliferation of gastric tumor cells." (PMID 33795838, 2021). "Moreover, treatment of FOXO3-Cyt-type gastric cancer cells (asterisks) with PI3K inhibitor or AKT inhibitor caused the accumulation of FOXO3 in nuclei, which was associated with the significant suppression of cell proliferation." (PMID 33795838, 2021). "Notably, phosphorylated AKT was detected in all FOXO3-High gastric cancer cell lines, suggesting the constitutive nuclear export of FOXO3 in these cells." (PMID 33795838, 2021). "Recently, the expression of miR-582 has been found to increase in gastric cancer, and it may activate PI3K/AKT/Snail axis through FOXO3 to regulate the proliferation and metastasis of gastric cancer cells." (PMID 34712324, 2021). "Finally, treatment of FOXO3-Cyt human gastric cancer-derived organoids with an AKT inhibitor significantly suppressed the survival and proliferation." (PMID 33795838, 2021). "For example, circ_0001368 suppresses the progression of gastric cancer via miR-6506-5p/FOXO3 axis." (PMID 32600379, 2020).
gastric cancer (continued). "For example, a recent study described a significant correlation between low expression of FOXO3 and a poor prognosis for gastric cancer patients, bringing evidence that FOXO3 could be a valuable prognostic biomarker for patients with gastric cancer." (PMID 32309538, 2013). "Thus, the inhibition of the PI3K-AKT pathway and nuclear translocation of endogenous FOXO3 may have therapeutic applications in the treatment of FOXO3-positive and cytoplasmic-type gastric cancer." (PMID 33795838, 2021). "On the other hand, Foxo3 is elevated in gastric cancer (GC) cells and promotes GC malignancy in vitro and in vivo by enhancing USP44 expression via targeting miR-143-3p." (PMID 34555810, 2021). "Moreover, Ba and colleagues demonstrated that gastric cancer cells secrete exosomes containing miR-155 which stimulated the remodelling of blood vessels in vivo by targeting the anti-angiogenic transcription factor Forkhead box O3 (FOXO3a)." (PMID 33572413, 2021). "In gastric cancer, a positive feedback interaction between AMPK and FOXO3 has been suggested, which potentially amplifies FOXO3 activity and contributes to enhanced antioxidant defense and metabolic reprogramming." (PMID 41008982, 2025). "Notably, gastric cancer cells with FOXO3-cytoplasmic distribution (FOXO3-Cyt) are sensitive to activated FOXO3-mediated growth suppression, and the inhibition of the PI3K-AKT pathway suppressed the survival and proliferation of gastric tumor cells associated with the nuclear accumulation of FOXO3." (PMID 33795838, 2021). "By down-regulating FOXO3 and CDKN1A, miR-96-5p could promote the proliferation of gastric cancer cells and bladder cancer cells respectively." (PMID 36473369, 2023). "It is thus possible that the FOXO3 expression is absent in FOXO3-negative type gastric cancers because of these mechanisms." (PMID 33795838, 2021). "In the present study, we examined whether or not FOXO3 plays a tumor-suppressor role in FOXO3-Cyt-type gastric cancer cells, in which FOXO3 is constitutively expressed and distributed to the cytoplasm." (PMID 33795838, 2021). "Furthermore, we were unable to examine the role of FOXO3 in the malignant progression of gastric cancer, as Gan mice do not develop metastasis." (PMID 33795838, 2021). "We thus examined whether or not FOXO3 can function as a tumor suppressor in FOXO3-Nuc-type gastric cancer cells." (PMID 33795838, 2021). "However, such information can help clarify the sensitivity of gastric cancer cells to FOXO3-mediated growth suppression, which may aid in establishing a therapeutic strategy using PI3K-AKT inhibitors or other compounds that induce the nuclear accumulation or activation of FOXO3." (PMID 33795838, 2021).
glioblastoma (51 papers, 2011 to 2026). The most malignant astrocytic tumor (WHO grade IV). "Another flavonoid, icariside II, attenuated the phosphorylation of forkhead box O3a (FOXO3a), increased the transcription of p21 and p27, and then caused cell cycle arrest in glioblastoma cells." (PMID 33321738, 2020). "Recent studies indicate that FOXO3 triggers chemoresistance in glioblastoma via the regulation of β-catenin and elevated FOXO3 expression is associated with poor patient prognosis." (PMID 31591479, 2020). "In addition, increased FOXO3 expression levels are associated with glioblastoma progression, mediated by autophagy and cell survival." (PMID 31488102, 2019). "However, there is increasing evidence showing that FOXOs, especially FOXO3, can support tumorigenesis in several cancer types: High expression of FOXO3 is associated with glioblastoma progression and prediction of poor survival of patients." (PMID 31488102, 2019). "To further test whether methylation by Set9 affects FoxO3 localization, we transfected a human glioblastoma cell line (U87) with FoxO3-GFP and either Set9 WT or the methyltransferase-deficient mutant of Set9 (H297A)." (PMID 22820736, 2012). "miR-27a, by targeting FOXO3, can either promote proliferation and invasion of glioblastoma cells, or suppress neuronal autophagy after traumatic brain injury." (PMID 37891184, 2023). "In glioblastoma, mTOR complex 2 (mTORC2) up-regulates the level of c-Myc and activates c-Myc by increasing the acetylation levels of FoxO1 and FoxO3 and then promotes glycolytic metabolism." (PMID 35689245, 2022). "Another study showed that the mammalian target of rapamycin complex 2 (mTORC2) can inhibit FOXOs via the acetylation of FOXO1 and FOXO3, thus promoting Myc activation and enhancing the Warburg effect in glioblastoma." (PMID 32629884, 2020). "In mammals TGFβ promotes hematopoietic stem cell quiescence by downregulating Akt activity and upregulating FoxO3 activity, and in glioblastoma cells TGFβ signaling induces Smad-FoxO transcriptional activation complexes that suppress proliferation." (PMID 21386132, 2011). "Additionally, it has been reported that FOXO3 expression accentuates invasiveness and tumor expansion in glioblastoma, pancreatic cancer and HeLa and melanoma MDA-MB-435 cells, being also correlated to perineural invasion in TNBC samples." (PMID 34771514, 2021). "In glioblastoma, FOXO3 triggers chemoresistance via the regulation of β-catenin." (PMID 33805928, 2021). "CX-4945 could be also applicable in the treatment of glioblastoma where CLK2 modulates phosphorylation of Forkhead box O3a (FOXO3a)/p27 and, consequently, cell cycle and survival of tumor cells." (PMID 33066143, 2020). "Interestingly, in the 17-metabolism gene risk signature we constructed, it has been reported that FOXO3 acetylation plays a central role in the regulation of glycolytic metabolism in glioblastoma, and the survival of GBM patients with FOXO3 acetylation is shorter." (PMID 33042807, 2020). "Using stem-like glioma-initiating cells derived from different human glioblastoma multiforme (GBM) samples, MTF activated AMPK which, in turn, activated differentiation marker FOXO3 as a transcription factor." (PMID 30241339, 2018). "In human neuroepithelial and glioblastoma cells, higher levels of myostatin and activin lead to a synchronous increase in the phosphorylated Smad2 and non-phosphorylated FOXO3 levels." (PMID 40149435, 2025).
glioblastoma (continued). "Several pre-clinical models reported the efficacy of metformin against glioblastoma cells, with different molecular mechanisms involving for example the chloride intracellular channel protein 1 (CLIC1), the AMP-activated protein kinase (AMPK), Akt and FOXO3 activation." (PMID 35326565, 2022).
pancreatic cancer (51 papers, 2010 to 2025). "In pancreatic cancer patients, high FOXO3 activation signatures are associated with a poor prognosis through the promotion of cancer stem cell properties." (PMID 31488102, 2019). "A functional polymorphism at miR-629-binding site in the 3′-UTR of FOXO3 gene confers a decreased risk of progression in pancreatic carcinoma." (PMID 29072689, 2017). "DP9 effectively disrupts the interaction between EGFR and Gal-3, and suppresses the Gal-3/EGFR/AKT/FOXO3 signaling pathway, thereby exerting anti-pancreatic cancer activity." (PMID 41295391, 2025). "Nitrated nateglinide (NO2-NAT) induced apoptosis in pancreatic cancer, while repaglinide inhibited forkhead box O3 (FOXO3), reducing neuroblastoma cell migration." (PMID 40227837, 2025). "Resveratrol inhibited the in vitro proliferation of pancreatic cancer cells and in vivo growth of orthotopic pancreatic tumors by activating FOXO3." (PMID 39334758, 2024). "Some studies have shown that long non-coding RNA00261 (Linc00261) inhibits pancreatic cancer progression by regulating the miR-552 5p/Forkhead Box O3 (FOXO3) axis." (PMID 38559560, 2024). "TPP+-containing mitochondria-targeting agents (e.g., Mito-metformin) inhibit pancreatic cancer cell proliferation via downregulation of the Akt/FOXO3/FOXM1 signaling axis in pancreatic cancer cells." (PMID 35756631, 2022). "The transcription factor Foxo3 is expressed a high level in CD44-positive cells from patients with pancreatic cancer and in PDAC cell lines such as Pan-1, Mia-Paca-2, and BxPC-3." (PMID 36605595, 2022). "FOXO3 was reported to suppress pancreatic cancer progression, where its knockdown facilitated the metastasis of pancreatic ductal adenocarcinoma by inducing EMT." (PMID 34363438, 2021). "As determined by RT‐qPCR, the expression pattern of BID was lower in the pancreatic cancer tissues relative to the adjacent normal tissues, and it was positively correlated with the FOXO3 expression pattern." (PMID 34363438, 2021). "In summary, the preceding results indicated that silencing of LINC00472 inhibited the expression pattern of BID through miR‐23a‐3p/FOXO3 to promote the proliferation and inhibit the apoptosis of pancreatic cancer cells." (PMID 34363438, 2021). "To further verify the effects of LINC00472 and FOXO3 on the pancreatic cancer cells in vivo, we subcutaneously injected the BXPC3 cells into nude mice to establish a tumorigenic model in vivo." (PMID 34363438, 2021). "Existing literature has reported that FOXO3 is poorly expressed in pancreatic cancer, thus signifying its vital significance in tumorigenesis and cancer development, which was consistent with our finding." (PMID 34363438, 2021). "Linc00261 inhibited the activation of the β-catenin/TCF4 pathway and cell metastasis by blocking miR-552-5p-induced targeting of FOXO3 in pancreatic cancer cells." (PMID 34178644, 2021). "Altogether, the preceding results indicated that LINC00472 knockdown amplified the tumorigenic capacity of pancreatic cancer cells by suppression of FOXO3." (PMID 34363438, 2021). "Subsequently, we predicted FOXO3 as a downstream target of miR‐23a‐3p in pancreatic cancer through the starBase database." (PMID 34363438, 2021). "The preceding results indicated that LINC00472 silencing stimulated the proliferation of pancreatic cancer cells and reduced apoptosis by down‐regulating FOXO3." (PMID 34363438, 2021). "In this study, we constructed both cellular and animal models to systematically investigate the signalling axis ZEB1/LINC00472/miR‐23a‐3p/FOXO3 in pancreatic cancer." (PMID 34363438, 2021). "Another study has indicated that the use of galectin-3 inhibitors can block the binding of galectin-3 to EGFR, thus inhibit the galectin-3/EGFR/Akt/FOXO3 axis and inhibit the occurrence and development of pancreatic cancer in vivo and in vitro." (PMID 30996686, 2019).
pancreatic cancer (continued). "In pancreatic cancer cells, FOXO3 is highly O-GlcNAc modified on S284 and this modification blocks FOXO3 function, leading to subsequent cancer cell growth." (PMID 31272438, 2019). "Pancreatic cancer patients with high FOXO3 activation signatures show a shorter overall survival rate than patients with low FOXO3 activation." (PMID 31488102, 2019). "Expression of miR-629 was markedly upregulated in pancreatic cancer and negatively correlated with FOXO3." (PMID 29072689, 2017). "MiR-629 regulated FOXO3 protein expression negatively at the posttranscriptional level and enhanced cell proliferation and invasion of pancreatic carcinoma in vivo and in vitro." (PMID 29072689, 2017). "It should be noted that FOXO3 expression was inversely correlated with miR-629 in pancreatic carcinoma tissues according to real-time PCR." (PMID 29072689, 2017). "miR-629 boosts proliferation and invasion in pancreatic cancer by targeting FOXO3." (PMID 38466341, 2024). "A positive correlation was identified between LINC00472 and FOXO3 in pancreatic cancer." (PMID 34363438, 2021). "As the critical roles of BID were identified in initiating the apoptosis of pancreatic cancer cells, we suggested that LINC00472 may up‐regulate the expression of BID through FOXO3 to induce the apoptosis of pancreatic cancer." (PMID 34363438, 2021). "Furthermore, analysis of a published clinical dataset (GSE15471) revealed that compared with normal pancreatic tissues, SIRT1 and CUL4B expression increased in pancreatic tumor samples, while FOXO3 and GRHL3 significantly decreased." (PMID 34163012, 2021). "Such regulatory axis was verified in both in vitro and in vivo settings, and our data demonstrated that LINC00472 silencing had fundamentally suppressed BID expression through miR‐23a‐3p‐mediated inhibition of FOXO3 to promote proliferation and inhibit the apoptosis of pancreatic cancer cells." (PMID 34363438, 2021). "Furthermore, our data revealed that LINC00472 silencing facilitated the progression of pancreatic cancer cells by inhibition of FOXO3 in vitro, while such interaction was evident during the tumorigenesis in vivo." (PMID 34363438, 2021). "Similarly, K-Ras signaling in pancreatic cancer activates NF-κB, which results in enhanced miR-155 expression, repressed FOXO3 expression and increased ROS accumulation." (PMID 35006436, 2020). "Moreover, we identified that miR-629 negatively regulates the oncogene FOXO3 by binding to the 3′-UTR of FOXO3 mRNA in pancreatic carcinoma cells." (PMID 29072689, 2017). "To further delineate, if NO actually induces the phosphorylation of FOXO3, we treated the human pancreatic cancer cell lines, Capan2 and SU.86.86 with a nitric oxide donor, Spermine/NONOate (Sper/NO), which resulted in an increased expression of both pERK and pFOXO3." (PMID 27367029, 2016). "However, progression of prostate and pancreatic cancers due to deregulation and nuclear translocation of phosphorylated FoxO3 have been documented." (PMID 22489133, 2012). "Moreover, overexpressing FOXO3 could reverse the stimulative effects on the pancreatic cancer cells mediated by LINC00472 silencing." (PMID 34363438, 2021). "To validate the tumour‐suppressive role of FOXO3 in pancreatic cancer, we conducted gain‐of‐function experiments, the results of which suggested that FOXO3 overexpression could suppress the proliferation of pancreatic cancer cells alongside inducing their apoptosis." (PMID 34363438, 2021). "Therefore, we speculated that LINC00472 may regulate the expression pattern of BID through FOXO3 to subsequently manipulate the development of pancreatic cancer." (PMID 34363438, 2021). "Therefore, exploring the regulatory mechanism of miR-629 and FOXO3 signaling may provide valuable clinical targets for pancreatic cancer therapy." (PMID 29072689, 2017).